LIF (LIF interleukin 6 family cytokine)
Diseases named in the same sentence as LIF in open-access papers (continued):
Sharing a sentence is not in itself a finding about the gene and the disease.
infection (50 papers, 2009 to 2025). The state of being infected such as from the introduction of a foreign agent such as serum, vaccine, antigenic substance or organism. "The protein expression of two proteins (IL-17C and IL-18) was significantly decreased and the protein expression of two proteins (TGF-α and LIF) was significantly increased in caspase-4-deficient cells compared to Cas9 cells following HK1651 infection." (PMID 40137780, 2025). "Recent studies indicate that LIF is readily induced by Ct infection, and that increased LIF expression is often linked to Ct-associated ectopic pregnancies in humans as well as severe oviductal pathology in mice." (PMID 36329823, 2022). "Gene expression analysis showed an increased expression of LIF in human neuroprogenitor cells three days after the infection by the Asian strain of ZIKV, but this association lost its significance after correcting the p-value (logFC = 1.41, p = 0.001, FDR = 0.44)." (PMID 34307186, 2021). "This systemic response was followed by an increase in additional inflammatory cytokines such as LIF, GM-CSF, and IL-15 at the peak of infection." (PMID 41472308, 2025). "In primary human microglia, LIF mRNA is present at very low levels under physiological conditions but can be upregulated in pathologies involving infection, inflammation, or injury." (PMID 39683685, 2024). "Twenty-four h after infection IL-10, LIF, M-CSF, IL-6, and IL-27 upregulation with the same mAbs was associated with protection in mice." (PMID 37289480, 2023). "Data collected 2 h after infection indicated that macrophages infected with Y. pestis pre-incubated with anti-LcrV 7.3 mAb (IgG1) significantly upregulated G-CSF, LIF, MIP-1β, TNF-α, MIP-1α, MCP-3, and MIP-2, while IL-2 and IL-28 were downregulated." (PMID 37289480, 2023). "It was demonstrated that LIF is readily induced by Ct infection, along with robust activation of type I interferon (IFN-β) signaling and upregulation of inducible nitric oxide synthase (NOS2) to control Ct replication in organoids." (PMID 36329823, 2022). "While LIF has been shown to promote regulatory T cells and inhibit the differentiation of type 17 helper T-cells, it is unclear how T cell responses are regulated by prolonged LIF production during Ct infection." (PMID 36329823, 2022). "Under normal circumstances, LIF is produced to maintain epithelial homeostasis and tissue repair, including the aftermath of Ct infection." (PMID 36329823, 2022). "The results from the organoid cultures provide strong experimental evidence supporting a potential role of LIF in epithelial transformation during Ct infection." (PMID 36329823, 2022). "It was first identified through comparing the transcriptomic profile of 1176 genes in DNA arrays of Ct-infected and mock-infected epithelial HeLa cells, in which 18 genes, including LIF, were up-regulated by Ct infection." (PMID 36329823, 2022). "Our microarray data revealed that acute Ctr infection consistently triggers LIF upregulation in all three donors." (PMID 30886143, 2019). "The DEGs involved in cytokine signaling were also up-regulated following infection with EV-F7, and included IL-6, IL-11, leukemia inhibitory factor (LIF), granulocyte-macrophage colony-stimulating (GM-CSF), and colony stimulating factor 2 (CSF2)." (PMID 30545363, 2018). "For example STAT1 can be activated by type I interferon, STAT3 can be activated by growth factors (e.g. EGF, LIF) and NFκB can be activated by reactive oxygen species, infection and other inflammatory cytokines, including IL-1β." (PMID 26678048, 2015). "Other proinflammatory cytokines that were moderately induced by USUV infection include LIF (member of the IL-6 superfamily), macrophage colony-stimulating factor, CXCL11, and granulocyte colony-stimulating factor, found to be increased on day 6 p.i. in comparison to the mock control." (PMID 39907280, 2025).
infection (continued). "Furthermore, ILC2-derived LIF was critical for establishing protective adaptive immunity to secondary infection with PVM virus, demonstrating the importance of the LIF signal in regulation of innate and acquired immunity." (PMID 39112698, 2024). "Additionally, diverse pathologies associated with neurodegenerative diseases, infection, ischemia, and traumatic injury are linked to increased levels of OSM, LIF, GDF-15, and FGF-2." (PMID 39683685, 2024). "Therefore, hiNeurons and hiAstrocytes were infected with Tha-eGFP or Th2P-4M-eGFP and treated with human recombinant IL-1β, IL-6, or LIF two hours after infection." (PMID 36680128, 2022). "LIF/LIFR signaling has been shown to alter the fate of epithelial cells during Ct infection." (PMID 36329823, 2022). "Considering the functional importance of LIF in preserving stemness in other models, we were interested in whether its induction during acute Ctr infection could contribute to infection-driven changes in homeostasis." (PMID 30886143, 2019). "This suggests that if the loss of MEK activity in MEF can be overcome, then the addition of 2i/LIF shortly after infection may enhance MEF survival." (PMID 30279419, 2018). "Interestingly, blocking LIF pathway activation with soluble neutralizing antibody at the time of infection increased the chlamydial load in the organoids, as visualized by immunofluorescence analysis at 14 d p.i. and confirmed in a separate experiment by qPCR of Ctr 16s." (PMID 30886143, 2019). "While it is unknown which cells are expressing LIF at increased levels following infection, given that Muller cells upregulate LIF in response to stress, Muller cells might serve as at least one of the cell types that produce LIF in response to B. cereus infection." (PMID 29661181, 2018). "To examine whether LIF plays an important role in promoting the adhesion of JAr spheroids to PL-PP-treated Ishikawa cells, we knocked down LIF expression in Ishikawa cells by shLIF lentiviral infection." (PMID 26839969, 2016). "qPCR results confirmed that acute infection disrupts endometrial receptivity (PAEP, LIF, ITGβ), affects cell proliferation (Ki67), and disrupts intercellular tight junctions (ZO-1) (p < 0.05)." (PMID 39600797, 2024). "Eight days after PVM infection, increased LIF was detected in the BAL of control mice compared with LIF-cKO mice, with lung ILC2s representing the predominant source of Lif as compared with T cells." (PMID 39112698, 2024). "The combination of both TMAO and CFT073 had significant additive effects on the release of IL-18R1 and synergistic effects on the release of IL-6, IL-24, IL-33, LIF, TGF-α, and LAP TGF-β1 compared to CFT073 infection alone." (PMID 37111409, 2023). "Similarly, LIF mRNA and protein are most detected at high levels in human fallopian tube samples obtained from ectopic pregnancies associated with Ct infections but not non-Ct infections." (PMID 36329823, 2022). "LIF, a member of the IL6 family, is involved in several pathological and physiological processes, including proliferation, regeneration, infection, inflammation, and immune response." (PMID 35481460, 2022). "SARS-CoV-2 infection also resulted in many cytokines and chemokines above baseline levels (all P < 0.05) throughout the infection, including IFN-γ, IL-1β, IL-4, IL-28, CXCL10, GM-CSF, LIF, CCL2, CCL7, MIP-1α, MIP-1β, RANTES, IFN-α, and IFN-β." (PMID 35634338, 2022). "Although the acute infection leads to activation of multiple paracrine growth factors (TGF-β1, EGF, FGF etc.), we identify LIF as a key player in the maintenance of stemness in tubal organoids." (PMID 30886143, 2019). "RT-qPCR was used to investigate the gene expression levels of miR-664 and predicted host target genes, LIF and NEK7, during infection with H7N9." (PMID 27166678, 2016). "LIF and NEK7 gene expression levels were rescued when the cells had been transfected with miR664i prior to infection." (PMID 27166678, 2016).
infection (continued). "Similar to the results observed in IL-33 and RWP challenge, PVM infection also resulted in a smaller proportion of pDCs expressing CCR7 (but not other chemokine receptors) in the absence of LIF." (PMID 39112698, 2024). "Our results are in agreement with previous findings showing an increase in serum IL-6, OSM, and LIF levels in BDL rats without any obvious signs of infection." (PMID 39391493, 2024). "Fluorescence imaging revealed that neither IL-1β, IL-6, nor LIF significantly modulated the percentage of eGFP+ hiNeurons or hiAstrocytes at 48 h post-infection." (PMID 36680128, 2022). "Moreover, LCN2/PEPCK/TNFR2 and LIF/FOS showed almost constant up- and down-regulated expression, respectively, across all three infection time-points studied in both groups." (PMID 35234615, 2022). "Similarly, IDO1 showed sixfolds increase, whereas LIF, IL6, CCL2, and VEGF each showed more than threefold increase in expression post infection." (PMID 32546788, 2020). "Significant reduction of LIF, LIF receptor (LIFR) and pSTAT3 was observed in endometrium of patients with dormant genital tuberculosis, suggesting a possibility that this infection could be one of reasons leading to RIF." (PMID 27304912, 2016). "In the absence of infection, CF-TG cells constitutively exhibited an inflammatory signature, including genes that encode molecules such as IL-1α, IL-β, IL-32, TNFSF14, LIF, CXCL1 and PLAU." (PMID 19399182, 2009). "At day 6 post-infection, multiple indicators of inflammation were noted including increased levels of T-cells, elevated levels of MCP-1 and CXCL10 chemokines in the cerebral spinal fluid (CSF), traumatic brain injury markers MMP-9 and LIF in the thalamus, and activated microglia." (PMID 40005568, 2025). "In glial cells, Tha and Th2P-4M infection did not induce significant expression of the selected proteins, although modest modulations of constitutively expressed proteins (IL-1β, IL-6, LIF) that were detected in astrocytic cells and/or in microglia-like HMC3 were recorded." (PMID 36680128, 2022). "Therefore, it is likely that LIF is produced preferentially, if not exclusively, upon intracellular infections for combating intracellular pathogens and assisting in tissue repair and epithelium homeostasis." (PMID 36329823, 2022). "The molecules that depicted significant increases in those mAb treated-mice at 96 h after infection were CXCL1 (KC), CCL2 (MCP-1), CCL3 (MIP-1α), CCL4 (MIP-1β), CXCL2 (MIP-2), CXCL5 (LIX), IL-1α, IL-6, G-CSF, M-CSF, and TNF-α (for all, P < 0.01) and IL-1β, IL-15, IL-10, and LIF (for all, P < 0.05)." (PMID 27642235, 2016). "Lentiviral infection with Jak1 shRNA, but not a control scrambled shRNA, markedly reduced survival of DRG neurons cultured in the presence of LIF." (PMID 37356718, 2023). "When mice were depleted of neutrophils at 8 weeks post-infection and evaluated at 12 weeks post-infection, they showed significant decrease in levels of CCL3 (MIP-1α), CCL4 (MIP-1β), CXCL1 (KC), LIF, G-CSF and M-CSF (Data not shown)." (PMID 27690127, 2016). "The brains of mice infected with HSV-LIF or HSV-Zeo, except for one LIF-treated mouse, contained virus that could be cultured at 3 days post infection (day 9 post induction, data not shown)." (PMID 23700462, 2013).
neurodegenerative disease (6 papers, 2018 to 2024). A disorder of the central nervous system characterized by gradual and progressive loss of neural tissue and neurologic function. "LIF possesses inconsistent and sometimes contradictory activities depending on the cell type and environment it acts in, making it a molecule of great interest in studies of neurodegenerative disease." (PMID 39683685, 2024). "Other groups have shown that in the efficacy of LIF in treating animal models of neurodegenerative disease may lie in its ability to modulate the immune system in addition to its pro-survival signaling." (PMID 30322390, 2018). "Neuroregulatory cytokines such as interleukin-6 (IL-6), ciliary neurotrophic factor (CNTF), leukemia inhibitory factor (LIF), cardiotrophin-1 and cardiotrophin-2 (CT-1 and CT-2), oncostatin-M and neuropoietin are useful in the treatment of neurodegenerative diseases and trauma." (PMID 35833035, 2022). "We chose to measure changes in the mRNA expression of interleukin-1β (IL-1β), tumor necrosis factor-α (TNF-α), Fas, interleukin-6 (IL-6), leukemia inhibitory factor (LIF), and interferon γ (IFN-γ) based on their potential involvement in neurodegenerative diseases." (PMID 33628191, 2021).
bacterial infections (3 papers, 2019 to 2024). "It will be interesting to determine whether ILC2-derived LIF also has roles during bacterial infections in which pathogen-associated molecular pattern-driven immune activation is important." (PMID 39112698, 2024). "However, the role of LIF in bacterial infection is not clear." (PMID 30733564, 2019).
heart disease (3 papers, 2013 to 2023). "While the data provided by PE and LIF are consistent with an additional role for CIP4 in heart disease, experimentation using the appropriate knock-out model is required to ascertain whether CIP4 is required for pathological hypertrophy in vivo." (PMID 23915320, 2013).
psychiatric disorder (3 papers, 2020 to 2022). A disorder characterized by behavioral and/or psychological abnormalities, often accompanied by physical symptoms. "In rodent models, leukemia inhibitory factor (LIF) is involved in cerebral development via the placenta, and maternal immune activation is linked to psychiatric disorders in the child." (PMID 36361987, 2022). "Induction of maternal LIF may be important for the effects of MIA on foetal brain development and psychiatric disease risk." (PMID 34903784, 2021).
cardiovascular diseases (2 papers, 2023 to 2025). "This family also encompasses several other cytokines, including IL-11, leukemia inhibitory factor (LIF), cardiotrophin-1, and oncostatin-M, which have been associated with the development of cardiovascular diseases." (PMID 40360833, 2025).
peripheral neuropathy (2 papers, 2016 to 2023). A disorder affecting the peripheral nervous system. "A pharmaceutical form of recombinant human LIF has been used in human clinical trials for recurrent implantation failure and chemotherapy-induced peripheral neuropathy." (PMID 27227407, 2016).
retinal disorder (2 papers, 2016 to 2022). Any disease or disorder of the retina. "Similarly, anti-angiogenic therapeutic DAMPs such as LIF, HS, and IL-33 are also in the early stages and their safety and efficacy profile is awaited for retinal disorders." (PMID 35269741, 2022). "LIF expression may also be altered in neuronal injuries and retinal disorders." (PMID 35269741, 2022).
brain diseases (1 paper, 2024). "We discuss how BDNF, NGF, IGF-1, and LIF could potentially be used for the treatment of brain diseases." (PMID 39598254, 2024).
hematopoietic cancers (1 paper, 2022). "Roles of LIF signaling in hematopoietic cancers was studied extensively when LIF was first identified, but has not been studied in recent years and may be worth revisiting with current research techniques." (PMID 35204717, 2022).
neurodevelopmental disorder (1 paper, 2021). A behavioral and cognitive disorder with onset during the developmental period that involves impaired or aberrant development of intellectual, motor, or social functions. "Based on research findings of the LIF/gp130 downstream pathway, we propose there are IL-6 family cytokine-based mechanisms of fetal neurodevelopmental disorders induced by maternal immune activation (MIA)." (PMID 34350170, 2021).
respiratory diseases (1 paper, 2016). "Thus, LIF may be a critical factor in the antiviral defense against RSV and other respiratory diseases such as influenza A. Whether this is solely mediated by miR-664, or by other mechanisms, remains unknown and will need to be investigated." (PMID 27166678, 2016).
LIF also shares sentences with these, for which no sentence is quoted: thyroid cancer (4 papers); abortion (2); acute myeloid leukemia (2); acute respiratory distress syndrome (2); amyotrophic lateral sclerosis (2); benign tumors (2); bladder cancer (2); endocrine disorder (2); Hypertension (2); IgA Nephropathy (2); neurological diseases (2); scoliosis (2); skin cancer (2); squamous cell carcinoma (2); steatosis (2); Thrombocytosis (2); abdominal aortic aneurysm (1); acute myocardial infarction (1); adenocarcinoma (1); Allergy (1); Anxiety (1); bacteremia (1); bacterial meningitis (1); Barrett esophagus (1); brain tumor (1); calpainopathy (1); Chlamydia infection (1); chronic hepatitis B infection (1); chronic pancreatitis (1); clear cell renal cell carcinoma (1).
A further 57 diseases each share a sentence with LIF in 1 paper.